SDHB (succinate dehydrogenase complex iron sulfur subunit B)
Diseases named in the same sentence as SDHB in open-access papers (continued):
Sharing a sentence is not in itself a finding about the gene and the disease.
schizophrenia (1 paper, 2024). A major psychotic disorder characterized by abnormalities in the perception or expression of reality. "In the TCA cycle, the genes CS, SDHA, and SUCLG2 were upregulated in schizophrenia but downregulated in ketosis, and SDHB was downregulated in both." (PMID 39125835, 2024).
serous ovarian carcinoma (1 paper, 2020). "In particular, murine SDHB-deficient serous ovarian carcinoma cells were shown to exhibit an unbalanced TCA cycle, with low production of fumarate and malate, owing to high succinate levels." (PMID 32575796, 2020). "Succinate accumulation following SDHB-knockdown also led to an EMT-like phenotype in a murine serous ovarian carcinoma cell line, which was attributed to H3K27 hypermethylation." (PMID 32575796, 2020).
somatotrophinoma (1 paper, 2022). "The most recent PitNET reported in association with an SDHB variant (c.587-591DelC frameshift) occurred in a 74-year-old female diagnosed with a macro somatotrophinoma on a background of metastatic PGL." (PMID 35938916, 2022).
squamous cell carcinoma (1 paper, 2014). A carcinoma arising from squamous epithelial cells. "Compared to other subtypes, squamous cell carcinomas (SQ) expressed more Glut-1 (p = 0.028), while adenocarcinomas (AD) expressed more SDHB in the stroma (p = 0.025)." (PMID 24387319, 2014).
steatosis (1 paper, 2025). Increased lipid within the cytoplasm of cells. "Mechanistically, FDXR deficiency disrupted iron-sulfur cluster assembly and reduced mitochondrial proteins such as succinate dehydrogenase complex iron-sulfur subunit B (SDHB), leading to mitochondrial dysfunction and steatosis." (PMID 40909793, 2025).
vascular occlusive disease (1 paper, 2021). "Among the patients who did not complete therapy there was the patient with the SDHB mutation whose treatment had to be stopped and a male patient of 69 years (with a history of vascular occlusive disease) who died from a cerebral insult 3 weeks after start of imatinib." (PMID 33546113, 2021).
tumor (318 papers, 2004 to 2026). "Previous studies have shown that the expression of SDHB is closely associated with the tumor’s invasive behavior and metastatic potential, particularly in PHL." (PMID 41333221, 2025). "Metastasis is more common in patients with a germline mutation in SDHB gene and having a primary tumor size greater than 5 cm at presentation." (PMID 41169441, 2025). "Some studies have reported that younger age, larger tumor size, extra-adrenal location of primary tumors, and the presence of mutations in the SDHB gene are associated with a higher metastatic risk." (PMID 40648440, 2025). "This aligns with international expert consensus, which identifies germline SDHB mutations as a key factor in risk stratification due to their strong association with aggressive tumor behavior and a lifetime metastatic risk of approximately 35–40%." (PMID 40648440, 2025). "Although no definitive characteristic has been identified to predict metastasis, large tumor size (> 5 cm), extra-adrenal localization, and SDHB loss are considered high-risk factors for metastasis." (PMID 40445576, 2025). "Established risk factors for metastasis, such as tumor size ≥ 5 cm and genetic mutations, particularly in SDHB, were likely contributors to this outcome." (PMID 41169441, 2025). "According to the literature, a higher risk of malignancy is noted in neoplasms with a size > 4–5 cm, that are secreting methoxytyramine, and are related to germline SDHB mutations." (PMID 40149362, 2025). "This uniform loss of SDHB expression across two histologically distinct neoplasms strengthens the interpretation that the germline SDHB variant is pathogenic, linking the molecular alteration to its phenotypic manifestation." (PMID 41426878, 2025). "The pathogenesis, progression, and metastatic potential of PPGL are closely associated with specific gene alterations, with SDHB mutations representing the most significant hereditary risk factor for tumor metastasis." (PMID 41234725, 2025). "In general, a large tumor size (>5 cm for PCCs, >4 cm for PGLs), vascular invasion, extra-adrenal location, and SDHB mutation-related tumors are suggestive of metastatic PPGLs." (PMID 40149362, 2025). "In patients with SDHB PPGLs, complete tumor removal and avoidance of capsular disruption to decrease the risk of local recurrence and dissemination of tumor cells is most important." (PMID 40149362, 2025). "The presence of an SDHB mutation (+0.04) further raises the prediction, consistent with its known link to aggressive tumor behavior." (PMID 40648440, 2025). "Predictors of metastatic development include large tumor size, extra-adrenal location, noradrenergic/dopaminergic phenotype, and presence of SDHB pathogenic variants." (PMID 38206185, 2024). "Resulting tumours recapitulated several human SDHB-associated PPGL characteristics, such as increased succinate levels, metabolic reprogramming, and transcriptional alterations related to defective electron transport and hypoxia." (PMID 39000369, 2024). "Our tumor cells exhibited positive granular, cytoplasmic reactions for SDHB and loss of FH expression, with FH+ endothelial cells serving as a positive internal control." (PMID 38793008, 2024). "Minimally invasive total adrenalectomy represents the preferred surgical standard over adrenal sparing surgery in cluster 1 tumors since these neoplasms harbor a high risk of recurrence and metastatic spread, especially if SDHB mutated and in cluster 3 tumors." (PMID 38543140, 2024). "Particularly, HPPS linked to SDHB mutation poses a significant clinical challenge due to its association with aggressive tumor features and a high risk of malignancy." (PMID 38633941, 2024).
tumor (continued). "Up-front surgery should be considered as first option in young patients, who often harbor SDHx mutations, especially in the SDHB gene, being at higher risk of metastatic spread with tumor growth." (PMID 38543140, 2024). "More importantly, recent retrospectively collected data suggest that subsequent periodic surveillance of asymptomatic carriers of SDHB pathogenic variants results in early tumor detection with improved clinical outcome." (PMID 38206185, 2024). "These animals still lack natural tumour development following an SDHB mutation and therefore fail to recapitulate the human disease situation faithfully." (PMID 39000369, 2024). "The current assessment of PGL metastatic potential relies on a comprehensive evaluation of several factors, including tumor size (≥5 cm), the presence of an SDHB mutation, a dopaminergic phenotype, and a high Ki-67 index." (PMID 39507200, 2024). "Our analysis found differences in the age of diagnosis for PPGLs caused by SDHB PVs, with Asians presenting earlier than Europeans with a tumor." (PMID 38481600, 2024). "SDHB pathogenic variants are associated with an earlier age of tumor onset and increased risk of tumor progression, metastases, and recurrence." (PMID 38947415, 2024). "Loss of SDHB immunoreactivity in tumor cells with SDHx mutations is reported with 100% sensitivity and 84% specificity, with a positive predictive value of 92% and a negative predictive value of 100%." (PMID 38667494, 2024). "Loss of FH expression indicates the presence of mutations in tumor cells, with SDHB applied as an additional marker to confirm the results of FH loss." (PMID 38793008, 2024). "Unsupervised clustering therefore confirmed the expected molecular profile of the A5 SDHB-mutant tumours as well as the pathogenicity of constitutional SDHB variants." (PMID 38978571, 2024). "Pathogenic variants in SDHB in PPGL patients are associated with a higher risk of tumor progression, and several studies have shown that SDHB pathogenic variation can be detected by the loss of SDHB staining in immunohistochemistry (IHC)." (PMID 39735644, 2024). "P/LP variants in certain genes (e.g., BRCA1/2, SDHB) identified in tumor-only sequencing of GISTs were almost exclusively germline in origin." (PMID 36593350, 2023). "Within the pseudohypoxia cluster, expression of PD-L1 was significantly lower in both SDHB- and non-SDHB-mutated tumours compared with sporadic tumours." (PMID 37033265, 2023). "In the univariant analysis, a hereditary PPGL, harboring a SDHB pathogenic variant, a higher excretion of urine normetanephrine and lower of urine epinephrine, a larger tumor size and having a sympathetic PGL were identified as predictors of recurrent disease." (PMID 38155946, 2023). "The absent SDHB staining on immunohistochemistry and the LOH in the tumor tissue are essentially confirmatory of the principle role of the SDHB pathogenic variant in the pathogenesis, aggressiveness and resistance of the macroprolactinoma in this patient." (PMID 38152133, 2023). "Regarding human Pheo/PGLs, transcriptome and methylome data revealed that high levels of promoter methylation of of Keratin19 (KRT19) were able to distinguish SDHB-mutated tumours from all other Pheo/PGL tumours." (PMID 37033265, 2023). "Our patient was found to have a pathogenic variant in SDHB, which is a tumor suppressor gene responsible for the production of the succinate dehydrogenase enzyme in mitochondria." (PMID 37024931, 2023). "Previous studies have found that SDHB immunohistochemistry (IHC) can predict SDHB germline gene mutation, and SDHB mutation is closely associated with tumor progression and metastasis." (PMID 37008946, 2023). "These tumours have a strong genetic determinism, and the presence of succinate dehydrogenase B (SDHB) mutations are highly associated with metastatic forms." (PMID 37033265, 2023).
tumor (continued). "Specifically, a higher degree of malignancy in HCC is associated with a lower expression of SDHB, which is significantly associated with advanced tumor stage and unfavorable prognosis." (PMID 37808079, 2023). "For SDHB-associated tumours, there was a higher proportion of M2 macrophage infiltration, with higher M2:M1 in aggressive SDHB PPGLs compared to indolent tumours." (PMID 35975974, 2022). "We subjected the FFPE tumor tissues obtained from patients harboring the SDHD:pH102R variant to IHC analysis of the expression pattern of the SDHB subunit." (PMID 36614070, 2022). "LOH at the SDHB locus was confirmed in the tumour tissue, suggesting a pathogenic role of the SDHB variant." (PMID 35938916, 2022). "Not surprisingly, given the higher rates of metastases that are seen in patients with underlying SDHB mutations, there is a bias within our cohort with 8 out of the 15 aggressive tumours harbouring an underlying SDHB mutation." (PMID 35975974, 2022). "Our most significant results were seen within the SDHB-associated tumours, although the significance remained when analysing the group as a whole." (PMID 35975974, 2022). "In PPGL, a relevant metabolic biomarker is SDHB immunohistochemistry which allows for the identification of patients with mutations in the SDHx tumour suppressor genes." (PMID 34834591, 2021). "People with SDHD mutations have the highest penetrance, with multiple tumours most frequently located in the head and neck region (parasympathetic), whereas SDHB mutations predispose carriers primarily to retroperitoneal PPGL (sympathetic)." (PMID 34021277, 2021). "One of the cases with SDHB mutation was 62 years old patient with 2 tumor foci, one at adrenal gland and one at retroperitoneum." (PMID 34181326, 2021). "Although the mechanism of developing malignant PPGL has not yet been identified, the authors suggested more rigorous follow-up of SDHB-negative tumours due to correlation between the loss of SDHB and adverse outcomes." (PMID 34356532, 2021). "Cluster 1 and possibly Cluster 3 PPGLs show a more aggressive phenotype (with the highest metastatic risk for SDHB mutations) compared with Cluster 2 tumours." (PMID 34834591, 2021). "Nevertheless, measurements of 3MT concentrations after primary surgery are very helpful for the detection of tumor progression in most patients with germline SDHB mutations." (PMID 34833055, 2021). "The upregulation of miR-483-5p in metastasizing PHEOs was confirmed by another study, in which two additional miRNAs, miR-101 and miR-183, were identified as related to SDHB mutations and aggressive tumor behavior." (PMID 34833055, 2021). "Conversely, immunonegative results in some VHL and NF1 mutated tumours compromise specificity of SDHB immunohistochemistry." (PMID 34834591, 2021). "When compared to other PGL syndromes, PGL4 has a higher rate of metastasis at diagnosis, risk of recurrence, and risk of developing other primary tumors due to SDHB’s role as a tumor suppressor." (PMID 33564614, 2021). "Tumor size, extra-adrenal location and germline SDHB mutations are independent risk factors for mPPGLs." (PMID 33959901, 2021). "The main prognostic factors are a large tumor volume, the existence or number of visceral metastases, and the presence of a mutation in the SDHB (Succinate dehydrogenase B) gene." (PMID 34052712, 2021). "On the one hand, a tumor hypermethylation phenotype can be caused by the SDHB gene inactivation; on the other hand, this phenotype can also lead to the loss of the second allele through the dysfunction of the SDHB gene expression regulators." (PMID 34833055, 2021). "SDHB expression in some SDHB-mutant Pheo/PGL tissues suggests that tumor heterogeneity occurs even in SDHB-associated tumors." (PMID 32150977, 2020). "The staining results showed loss or decreased SDHB expression but preserved SDHA expression in the examined neoplasms, as compared with adjacent normal tumor tissues." (PMID 33031286, 2020).
tumor (continued). "These experiments have demonstrated that SDHB-deficient tumor cells use more extracellular pyruvate than normal cells due to their insufficient biosynthetic capacity to meet the demands of this amino acid." (PMID 33077733, 2020). "The tumor had a mixed histology pattern of high-grade papillary and collecting duct carcinoma and characteristic pale eosinophilic cytoplasmic inclusions like SDHB-deficient RCC; this is the first report that identifies SDHA inactivation in RCC93." (PMID 31372201, 2019). "The second patient (SNP-004) with PCC who had a germline SDHB mutation had a 47% reduction in tumour volume as best response after 23 cycles but stopped treatment due to progression in non-target lesions together with evidence of clinical progression." (PMID 31105270, 2019). "Because of the loss of SDHB protein observed in tumor versus normal tissue, we considered the possibility of somatic alterations to the paternal SDHA wild‐type allele." (PMID 30680959, 2019). "For comparison, SDHB staining in endothelial cells from the SDHA wild‐type ccRCC tumor and SDHA‐mutated GIST tumor is shown in S1C and S1D, respectively." (PMID 30680959, 2019). "This tumor showed the SDHB p.Arg38Gln variant in a homozygous fashion, which was also homozygous in DNA isolated from normal tissue from the same dog." (PMID 31052272, 2019). "Thirteen patients (24 per cent) had no associated signs or symptoms at the time of diagnosis, and the tumour was identified as a result of presymptomatic screening of known SDHB mutation carriers (11 patients) or as an incidentaloma." (PMID 29951630, 2018). "Low SDHB expression in cancer tissues was associated with tumor dedifferentiation (p < 0.01) and borderline associated with advanced pathologic stage (p = 0.06)." (PMID 29449614, 2018). "In 2009, immunohistochemical analysis of tumor samples from patients with Carney triad demonstrated a loss of the SDHB protein." (PMID 30456751, 2018). "In the Netherlands, tumour screening in SDHB‐linked families is advised from the age of 18 years onwards." (PMID 29951630, 2018). "Pediatric patients with PHEO harbor an SDHB mutation in 13.6% of cases, and the majority develop this tumor at ≥8 yo." (PMID 29755524, 2018). "And only correlation of germline SDHB mutations with tumor aggressiveness is indicated as an established fact." (PMID 29504908, 2018). "SDHx- and especially SDHB-mutated tumours have high metastatic potential, while also exhibiting a hypermethylator phenotype." (PMID 28327598, 2017). "The second case, GIST 117, carried a germline SDHB splice site mutation (c.423 + 1G > A) and exhibited loss of the wild type allele in the tumor." (PMID 28768491, 2017). "Adding strength to the analysis, sequencing of the patient’s tumor DNA demonstrated LOH of the wild type SDHB allele." (PMID 28768491, 2017). "On the other hand, SDH mutations cause intra-adrenal tumours less commonly; 25% of SDHB-related tumours are phaeochromocytomas while the frequency of intra-adrenal tumours in SDHD, SDHA and SDHC are even lower." (PMID 29166454, 2017). "The somatic ATRX mutation in these tumor samples was accompanied by an inherited mutation in the SDHB gene." (PMID 28187001, 2017). "All of these tumor syndromes are characterized by loss of SDHB in tumor immunohistochemistry staining." (PMID 26294907, 2015). "We validated this finding using quantitative reverse transcription–PCR and confirmed that the highest expression is displayed by SDHB-mutated tumours." (PMID 25625332, 2015). "All SDHB-mutated tumors were sensitive to camptothecin, and one such tumor was extremely sensitive, supporting a potential role for TOP1 inhibitors in treating metastases." (PMID 24516563, 2014). "The C228T-positive tumor and three additional PGLs carried a SDHB mutation, while nine cases were WT for both gene mutations; however, the limited number of cases does not allow for associations between gene mutations in the PGL entity." (PMID 24803525, 2014).